ESR1 (estrogen receptor 1)
Diseases named in the same sentence as ESR1 in open-access papers (continued):
Sharing a sentence is not in itself a finding about the gene and the disease.
Infertility (continued). "The reproductive phenotypes of the Esr1 KO male rats are similar to that of the Esr1 KO mice, which include infertility, decreased testicular weight, and sperm in the epididymal tail." (PMID 35681843, 2022). "PAEP, ESR1, and PGR are indeed normally finely regulated, and their abnormalities in patients with luteal phase defects are associated with infertility." (PMID 31375021, 2019). "Global Esr1 knockout female mice were generally considered to be infertile in adulthood, which is similar to acyclic adult animals." (PMID 30319547, 2018). "For instance, Esr1 knockout mice have impaired spermatogenesis with reduced sperm numbers and abnormal sperm function leading to infertility." (PMID 24025394, 2013). "ESR1 knockout mice showed reproductive impairment as anovulation and complete infertility." (PMID 35707481, 2022). "In mammals, global knockout of Esr1 in mice resulted in infertility with primary amenorrhea." (PMID 30319547, 2018). "Indeed, human fertility is under the control of estrogens and ESR1 and/or ESR2 gene mutations and polymorphisms have been associated with reproductive defects in both men and women, including abnormal timing of puberty and infertility." (PMID 38978624, 2024). "Furthermore, the FSHR rs6165 GG, rs6165 AA, ESR1 rs9340799 GA, and rs2234693 TC gene combination enhanced the protective effect of FSHR gene variants and was associated with a reduced risk of fibrocystic mastopathy in infertile women." (PMID 37239044, 2023). "ESR1 displayed mutations in five of eight infertile men and none in fertile controls, and could be further explored as a gene target for male infertility." (PMID 37895049, 2023). "Disruption of ESR1 has been associated with alterations of spermatogenesis and subsequently infertility in mice, therefore suggesting that the apparent decrease in esr1 transcript in the testis may contribute toward the observed decline in fertilization success at this concentration." (PMID 27120497, 2016). "Therefore, the testicular effects of Lgr4 on controlling the Esr1 expression might potentially explain the consequence of infertility in Lgr4-null mice." (PMID 25188337, 2014). "Research utilizing a mouse model has emphasized ESR1's critical role within the uterus and neuroendocrine system, with female mice lacking ESR1 facing infertility due to impaired ovarian and uterine function." (PMID 38910609, 2024). "Earlier genetically designed experiments on knockout mice have shown a fascinating association between the absence of ESR1 and the PCOS symptoms of intermittent estrus, infertility, elevated androgen levels, and hemorrhagic follicle formation." (PMID 36831054, 2023). "As well as for ESR1 and ESR2, VDR/KO mice (from in vivo studies) are infertile." (PMID 35353297, 2022). "The absence of estradiol ESR1 and 17 beta membrane fractions can induce male reproduction abnormalities to infertility." (PMID 31849431, 2019). "However, ESR1/ERα, ESR2/ERβ and PGR/PGA showed marked differences in fertile and infertile patients from the control and OE groups." (PMID 31878927, 2019). "In mice, females lacking the ESR1 gene are infertile and non-receptive to males." (PMID 33477862, 2021). "When samples from the control infertile group (group 1B) were compared with samples from the OE infertile group (group 2B), higher levels of the NR5A1 (P < 0.0001), STAR (P < 0.0001), CYP19A (P < 0.01), ESR1 (P < 0.05) and ESR2 (P < 0.001) transcripts were detected in group 1B than in group 2B." (PMID 31878927, 2019).
lymph node metastasis (104 papers, 2005 to 2026). "A cervical lymph node metastasis showed double ESR1 mutations, the Y537S and the E380Q ESR1 mutation, with a MAF of 12.8 and 2.69%, respectively." (PMID 29166868, 2017). "Low expression of lnc-CCDC170–4:1 and ESR1 are associated with lymph node metastasis and FIGO stage, so it may be a potential biomarker to evaluate the prognosis of cervical cancer." (PMID 39206151, 2024). "Moreover, low expression of lnc-CCDC170–4:1 and ESR1 are associated with lymph node metastasis and FIGO stage, so it may be a potential biomarker to evaluate the prognosis of cervical cancer." (PMID 39206151, 2024). "Interestingly, for the matched lymph node metastasis, the opposite trend was observed with decreased ESR1 topic and increased FOXM1 topic, showcasing transcriptional plasticity within a patient." (PMID 36318267, 2022).
colon carcinoma (97 papers, 2007 to 2026). "ESR1 encoding estrogen receptor α expresses very low in normal colon mucosa, but an increase in ESR1 expression results in poor outcomes in patients with colon cancer." (PMID 39334689, 2024). "Treatment with celecoxib, a COX-2 specific inhibitor, suppressed DNA methylation in the promoter region of ESR1 encoding the estrogen receptor α in rat colon tumor cells." (PMID 32054946, 2020). "Moreover, methylation of ESR1 was significantly associated with UC-related colon cancer." (PMID 36532769, 2022). "CDH2 and ESR1, two of the key genes in the 5hmC metastasis signature, were significantly hypermethylated at their promoters (P < 0.0001) in colon cancer compared to normal colon." (PMID 40241172, 2025). "In an MBD-seq dataset for colon tumour and liver metastasis tissue, we confirmed that CDH2 and ESR1 were hypermethylated in primary colon cancer consistent with our findings." (PMID 40241172, 2025). "The two main subtypes of ERs are ERα (encoded by oestrogen receptor 1, ESR1) and ERβ (encoded by oestrogen receptor 2, ESR2), which are differentially expressed in normal colon tissue as well as in colon cancer cells." (PMID 38137047, 2023). "Intriguingly, one report has shown increased ESR1 promoter methylation in colon cancer, as a function of age." (PMID 26251034, 2015). "While they operate through different mechanisms and serve distinct functions, it is likely that they indirectly influence each other during metastatic processes and that the genes in this cluster which also include PLG and ESR1 constitute a 5hmC metastatic signature for colon cancer." (PMID 40241172, 2025). "In addition, activated ESR1 stimulates the expression of tumor promoters and promotes colon cancer cell survival and metastasis; thus, blocking ESR1 expression offers a potential therapeutic opportunity for colon cancer." (PMID 39334689, 2024). "Next, we tested the effect of the functional absence of ESR1 on colon cancer metastasis in vitro as well as in vivo." (PMID 38549115, 2024). "However, ESR1 function in colon cancer has not been elucidated, because its expression was limited in normal and malignant colonic epithelium." (PMID 31159758, 2019). "The authors found that the compounds of LWDHW may play an important role in esophagitis and colon cancer by regulating the expression of C-C chemokine receptor 2 (CCR2), estrogen receptor 1 (ESR1), peroxisome proliferator-activated receptor gamma (PPARG), and retinoic acid receptor alpha (RARA)." (PMID 30846939, 2019). "Furthermore, molecular docking results indicated the stable binding connections between TQ/5-FU and the hub targets, i.e., MAP2K2, CASP3, PIK3CA, ESR1, CYP3A4, CYP2C19, and CYP2C9, suggesting that TQ, in combination with 5-FU, may treat colon cancer by modulating these hub targets." (PMID 39334689, 2024).
melanoma (97 papers, 2008 to 2026). A malignant, usually aggressive tumor composed of atypical, neoplastic melanocytes. "Circulating methylated ESR1 encoding Estrogen Receptor alpha (ER-α) was also correlated with worse prognosis in melanoma patients." (PMID 39156972, 2024). "Notably, the ESR1 gene (encoding ERα) resulted in a major target of miR-221/222 and its knockdown mirrored the effect of miR-222 overexpression on melanoma invasive activity." (PMID 29996493, 2018). "H3K27ac ChIP–seq in mouse melanoma cell lines revealed female ∆Ecad-specific signatures linked to β-catenin (LEF1), oestrogen receptor-α (ESR1) and YAP1/TEAD." (PMID 40500450, 2025). "Complementary studies in melanoma found that the NuRD complex is recruited to the Twist-binding chromatin region of the ESR1 gene by Twist to decrease H3K9ac and increase H3K9me1 in melanoma, consistent with the repressive role of NuRD in ERα expression." (PMID 37568822, 2023). "All but ESR1, PAX8, PGR, TMEFF2, were associated with prognosis of breast, cervical, colorectal, head and neck, liver, lung, melanoma, ovarian, pancreatic, renal, or urothelial cancers." (PMID 34680205, 2021). "Three SNPs (rs12662670 and rs2234693 from ESR1 and rs5742694 from IGF1) were thus excluded for further analyses, even though their χ2 statistics showed significant association with melanoma risk." (PMID 32150843, 2020). "Esr1 regulation by β-catenin was validated in human melanoma using iCRT3." (PMID 40500450, 2025). "On the other hand, SNPs rs2234693 (p = 0.035 < 0.038 critical value) and rs827421 (p = 0.018 < 0.019 critical value) in ESR1 had only borderline Benjamini–Hochberg corrected significant genotypic differences between melanoma cases and healthy controls in the GENEVA dataset." (PMID 32150843, 2020). "The ESR1 SNPs rs2234693 and rs827421 may play a role in melanoma patients, but further analysis is needed." (PMID 32150843, 2020). "In line with this, the possible role of ESR1 SNPs in melanoma requires further investigation." (PMID 32645881, 2020). "On the other hand, ESR1 SNPs rs2234693 and rs827421 only slightly presented Benjamini–Hochberg significances of their genotypic and dominant genetic model differences between melanoma cases and controls in the GENEVA cohort." (PMID 32150843, 2020). "The ESR1 SNPs are still likely to play a role in melanoma development." (PMID 32150843, 2020). "It was noted that rs2234693/ESR1 did not present a significant Benjamini–Hochberg corrected association with melanoma risk in the GEM set might be a result of HWE deviation." (PMID 32150843, 2020). "MiR-222/221 directly targets growth factor receptor-bound protein 10 (GRB10) and estrogen receptor-alpha (ESR1), which participate in promoting melanoma invasion." (PMID 39201498, 2024). "Other sex hormone receptors (Esr2, Gper1, Ar and Pgr) were not expressed in murine melanoma, and only ∆Ecad female lines expressed both Grpr and Esr1." (PMID 40500450, 2025). "Expression of ESR1 and ESR2 in melanoma progression has been controversial." (PMID 32150843, 2020). "Loss of terminal differentiation traits, as observed by inactivation of ESR1, PTPRS, or the metastasis suppressor gene GATA3, may reflect the intrinsic capacity of melanoma cells to gain plasticity, and to progressively acquire changes that trigger metastatic dissemination." (PMID 28578692, 2017). "In this regard, EGFR, PTEN, ESR1, FGFR2 and ERBB2 were more frequently detected in CSF ctDNA than in blood in a cohort of NSCLC and BC as well as in patients with melanoma and negative CSF cytology." (PMID 34207653, 2021).
hepatocellular carcinoma (93 papers, 2009 to 2026). A malignant tumor that arises from hepatocytes. "The evidence has linked overexpression of Esr1 (estrogen receptor 1) gene with estrogen-induced hepatocellular carcinoma in mice." (PMID 20682481, 2011). "ESR1 was associated with overall survival in all hepatoma patients (p = 7.19e–5), indicating that it may inhibit the development and progress of hepatoma." (PMID 35872841, 2022). "Indeed, the polymorphisms in the 5′ end of the ESR a (ESR1) gene have been shown to be associated with an increased hepatocellular carcinoma risk, supporting the involvement for the estrogen-ESR axis in the estrogen-induced hepatocarcinogenesis." (PMID 21526182, 2011). "The expression of estrogen receptor alpha (ERα, encoded by ESR1) has been shown to be associated with the prognostic outcomes of patients in various cancers; however, its prognostic and mechanistic significance in hepatocellular carcinoma (HCC) remain unclear." (PMID 34145394, 2021). "The same inversely correlated relationship was also observed in hepatocellular carcinoma (HCC) cells where the overexpression of miR-18a caused a downregulation of ESR1 and a stimulation of proliferation." (PMID 32365562, 2020). "It is particularly noteworthy that SRC and ESR1 seem to have a significant effect on the survival curve of patients with hepatocellular carcinoma." (PMID 38474604, 2024). "Estrogen Receptor 1 (ESR1) expression is lost or diminished in human Hepatocellular carcinoma (HCC) cells and liver tumors, suggesting a potential protective role of estrogen signaling in HCC and that low ESR1 gene expression plays." (PMID 38994338, 2024). "In hepatocellular carcinoma, miR-939-3p induced epithelial-mesenchymal transition via targeting estrogen receptor 1 (ESR1)." (PMID 38420020, 2024). "The network analysis and survival analysis results identified ESR1 as an essential protective factor in hepatoma treatment." (PMID 35872841, 2022). "Survival analysis indicated that a high/ESR1 gene expression had a relatively good prognosis for patients with hepatoma (p < 0.05)." (PMID 35872841, 2022). "Liver anticancer potential for BBR is mainly due to the regulation of hepatoma cells via interactions among ESR1, TB52, PTGS2, CCDN1, and MAPK1 pathways, which act on Hub-nodes in those interlinked pathways." (PMID 34885950, 2021). "In hepatocellular carcinoma, ESR1 suppresses circular RNA-SMG1.72 and this leads to the downregulation of miR-141-3p, eventually inhibiting cell invasion." (PMID 33534778, 2021). "miR-18a directly targets ESR1 and has been shown to promote estrogen receptor alpha (ESR1) dependent proliferation in hepatocellular carcinoma cells." (PMID 21364938, 2011). "In the current studies, the exploration and further value of PIK3CG in hepatoma may be lower than ESR1." (PMID 35872841, 2022). "ESR1 has also been reported as a candidate tumor suppressor gene for hepatoma." (PMID 35872841, 2022). "ESR1 is the potential key gene that is beneficial for the survival of hepatoma patients." (PMID 35872841, 2022). "Besides, ESR1 was found to inhibit the development and progress of hepatoma." (PMID 35872841, 2022). "Moreover, ESR1, the core protein, which interacts with most nodes in this sub-network, of the network that is deregulated from BCLC stage 0 HCC, have been shown to be associated with an increased hepatocellular carcinoma risk." (PMID 21526182, 2011). "This study systematically elucidates the potential mechanisms of AAI, an environmental pollutant, in inducing hepatocellular carcinoma, identifying key targets including CYP1A2, ESR1, and AURKA." (PMID 40864066, 2025). "It is interesting to note that after visualization, the main core targets of mignonette in treating hepatocellular carcinoma are SRC, EGF, ESR1, AKT1, PI3KR1, AR, and CDK1." (PMID 38474604, 2024). "NR1I2, ESR1, ALPL, MME, IGF1, NR3C2 and PTGS2 were differentially low expressed in hepatocellular carcinoma tissues." (PMID 38842135, 2024).
hepatocellular carcinoma (continued). "Estrogen receptor alpha (ERα, ESR1) has been implicated in various liver diseases, including NAFLD, chronic hepatitis B (CHB), liver cirrhosis (LC), and hepatocellular carcinoma (HCC)." (PMID 38136219, 2023). "miR-9-5p enhances the tumorigenic ability of hepatocellular carcinoma cells by targeting CPEB3 and ESR1, but miR-9 plays a tumor suppressor role in hepatocellular carcinoma by regulating IGF2BP1, Sox11, and P21." (PMID 36421826, 2022). "By comparing the mRNAs in the ceRNA subnetwork with the mRNAs in the PPI subnetwork, three common mRNAs (ESR1, CXCL12 and IRF4) were obtained, which should play an important role in the development of hepatocellular carcinoma and used as follow-up research objects." (PMID 36855431, 2023). "CCL23 has been found to be underexpressed in hepatoma cells, and this could lead to CCL23 deletion and reduced CCL23 inhibition via the ESR1/CCL23/CCR1/AKT regulatory axis in liver cancer progression." (PMID 36425563, 2022). "The results obtained in this study also indicated that treatment with (+)-catechin could significantly increase the expression levels of ESR1 and CAT in human hepatocellular carcinoma cells." (PMID 36193154, 2022).